CD63 (CD63 molecule)
Diseases named in the same sentence as CD63 in open-access papers (continued):
Sharing a sentence is not in itself a finding about the gene and the disease.
COVID-19 (continued). "In COVID-19 patients, an expansion of CD63+ neutrophils was apparent, and this increase was more profound in patients with severe disease." (PMID 33003471, 2020). "In addition, CD63 expression was increased in plasma cell-free RNA sequences of severe COVID-19 patients." (PMID 38262689, 2024). "ACE2+ EVs were enriched in CD63+ EV subsets from COVID-19 patients." (PMID 35058437, 2022). "Interestingly, when critically ill COVID-19 patient plasma is incubated with platelets from healthy volunteers, there is a similar increase in platelet activation markers (P-selectin, CD63)." (PMID 35371058, 2022). "We also observed significant up-regulation of CD66b, CD177, CD11b, CXCR4, CD147 (the receptor that binds the spike protein of SARS-CoV-2), and CD63 in mature neutrophils from COVID-19 patients compared to healthy controls, as well as significant down-regulation of CXCR2." (PMID 34548411, 2021). "Our analyses also suggest a differential miRNA expression between CD63+/CD81+/CD9+ serum small‐EVs from mildly and severely ill Covid‐19 hospitalized patients, which will require further evaluation." (PMID 34122779, 2021). "Interestingly, plasma from COVID-19 patients triggered platelet activation in vitro, as demonstrated by a significant increase in platelet P-selectin and CD63 surface translocation and platelet-leukocyte aggregates formation, which was dampened by pretreatment with IL-6 receptor inhibitor." (PMID 34977191, 2021). "The mild COVID-19 group were overrepresented in population 0 (CD16+CD10+CD62L+CXCR2+CXCR4+) and population 7 (CD16+CD10+CD63+PD-L1hiLOX-1+CD62Llo)." (PMID 39253969, 2024). "We observed that certain markers (CXCR4, CXCR2, CD63, and LOX-1) showed a correlation with COVID-19 disease severity." (PMID 39253969, 2024). "Considering the overall median fluorescence intensity (MFI) for specific EV markers (i.e., tetraspanins CD63, CD9 and CD81) we observed that only EV-specific tetraspanin CD81 was significantly higher in COVID-19 patients than controls (P<0.05)." (PMID 37207201, 2023). "Our results suggest enrichment for EV specific markers CD63, CD81, and CD62P and procoagulant PS in COVID-19 (+) patient plasma EVs compared to healthy donors." (PMID 36564503, 2022). "Flow cytometry confirmed the enrichment of EV specific markers CD63, CD81 and CD62P in COVID-19 (+) patient LEVs compared to healthy donors and COVID-19 (+) patient SEVs." (PMID 36564503, 2022). "On the other hand, plasma of severely-ill COVID-19 patients also induces platelet CD62P and CD63 expression relative to control plasma, providing evidence that platelet activation in COVID-19 is also regulated by plasma components." (PMID 35419008, 2022). "Tetraspanin monoclonal antibodies (anti-CD9, anti-CD63 and anti-CD81) have been demonstrated to inhibit the COVID-19 entry stage." (PMID 36101528, 2022). "Distinct immunotypes were evident in COVID-19 patients, with altered expression of several receptors involved in activation, adhesion, and migration of granulocytes (e.g., CD62L, CD11a/b, CD69, CD63, CXCR4)." (PMID 34548411, 2021). "Of interest, an altered expression of various receptors involved in migration, adhesion and activation, including CXCR4, CD63 and CD69, have been reported in COVID-19, highlighting specific immunophenotypes with predictive potential for clinical outcomes." (PMID 34944610, 2021). "We also found an increased expression of CD63, ITGB2, CD37, CD2 and IL23R markers and the reduction in CXCR4, CD69, CD48, ICAM1 and S100A10 markers in COVID-19-derived NK-T cells compared to controls." (PMID 34944610, 2021). "On the other hand, CD63, a marker for azurophilic degranulation, was markedly upregulated in LDNs of patients with mild and severe COVID-19 (an effect not evident in whole blood)." (PMID 39253969, 2024). "Previous studies have found that both CD63 and ILR1N correlate with COVID-19 severity." (PMID 39712003, 2024).
COVID-19 (continued). "Population 5 (CXCR2–CD16+CD10–CD63–) was almost exclusively derived from patients with COVID-19 and displayed low CD63 expression, suggesting an immature non-degranulated phenotype." (PMID 39253969, 2024). "CD63 exosome marker expression was higher in EVs of healthy-pregnant subjects and COVID-19-pregnant subjects compared to EVs of non-pregnant subjects (p = 0.0149, p = 0.0028, respectively)." (PMID 37560162, 2023). "Common cell markers of platelet activation, including P-selectin and CD63, are also increased in critically ill COVID-19 patients, but not those with mild disease." (PMID 35371058, 2022). "EVs collected from the serum of both healthy controls and patients with COVID-19 were confirmed by transmission electron microscopy, and western blotting confirmed the expression of CD9, CD63, and flotillin-1, while calnexin and haptoglobin expressions were negative." (PMID 36451245, 2022). "Analyzing these data together with platelet activation changes induced by plasma from COVID-19 patients revealed strong correlations among CD63, CD32 and C3aR, but not with CD62P (top 4x4 square of correlations)." (PMID 35309299, 2022). "In contrast, however, CD63 and CD32 were increased on control platelets following incubation with plasma from the COVID-19 inpatient group compared to platelets treated with plasma from the COVID-19 convalescent group." (PMID 35309299, 2022). "In addition, despite their CD69 expression, activated eosinophils in severe COVID-19 patients displayed lower levels of CD11a, CD63, and CD66b compared to the CD69+ eosinophils from patients with moderate COVID-19." (PMID 34548411, 2021). "However, CD63 expression by platelets co-cultured on the endothelial monolayer did not appear to be affected by COVID-19 plasma, except for D4 control plasma, which triggered a 0.7 ± 0.4-fold decrease in this marker (p = 0.005)." (PMID 37215546, 2023). "Therefore, the up-regulation of CD62L, CD63, CD11b, and CXCR4 on basophils observed during the acute phase of COVID-19 and their normalization after viral clearance might imply a role of this phenotype in COVID-19 pathophysiology." (PMID 34548411, 2021). "The relationship between CD63, CD32, C3aR and clinical disease indicated by ferritin levels and organ damage biomarkers in the blood suggested that the platelet activation potential of plasma from COVID-19 patients might provide additional insights into disease pathogenesis." (PMID 35309299, 2022). "Western blotting analysis displayed EV specific tetraspanin markers (CD63 and CD81) expression of healthy donor SEVs/LEVs and COVID-19 (+) patient SEVs/LEVs and EDP as negative control." (PMID 36564503, 2022). "Platelets of COVID-19 patients express increased surface levels of CD62P and CD63 relative to either healthy controls or non-COVID-19 pneumonia patients, demonstrating augmented basal platelet degranulation." (PMID 35419008, 2022). "However, unlike what is typically seen with activated mature blood eosinophils, we found here increased CD125 and CD63, a reduction in CD44, and a lack of change for HLA-DR and CRTH2 in COVID-19." (PMID 40710346, 2025).
Allergy (28 papers, 2005 to 2025). An allergy is an immune response or reaction to substances that are usually not harmful. "An increase in CD63 on the surface of basophils cells has also been associated with allergic reactions or diseases." (PMID 33669497, 2021). "Basophil CD63% was significantly increased in subjects with allergy to shrimp and prawn (p < 0.05% for all)." (PMID 40572728, 2025). "Some studies have suggested a correlation between CD63 expression and the severity of allergies to peanut and cow’s milk." (PMID 40572728, 2025). "This study aims to confirm the OCT3/CD63 interaction and to delve into its plausible role in histamine release and the onset of allergic reactions, both in controlled in vitro settings and in live animal models of allergic reaction." (PMID 40652190, 2025). "Four hours after the allergen challenge, we evaluated the frequencies of activated basophils (IgE+CD200R3+CD63+) in the spleens, which are major effector cells mediating allergic reaction." (PMID 40432060, 2025). "Over the last years, the potential value of the BAT-FC with different basophil activation markers (CD203c and CD63) in PC allergies has been investigated." (PMID 38612700, 2024). "CD63, as a marker of basophil activation, is widely used in the basophil activation test in the diagnosis and monitoring of allergic diseases." (PMID 37208718, 2023). "Basophil activation tests to GOS and Blo t using whole blood from seven patients with GOS allergy and concomitant IgE sensitization to Blo t showed typical dose-dependent expression of CD63." (PMID 35386657, 2022). "CD63 is highly relevant to an IgE-mediated allergic reaction, which is correlated with histamine through intracellular diamine oxidase." (PMID 33291359, 2020). "This is consistent with our data, which also support more extensive basophil activation (typically up to 20% of basophils expressing CD63 and CD203c) during peanut-induced allergic reactions." (PMID 28342911, 2017). "CD63 peanut/anti-IgE and CD-sens values can be used to estimate the severity and threshold of allergic reactions during OFCs." (PMID 25567046, 2015). "As indicated by the key roles of mast cells and basophils in allergy, wheal diameter and expression levels of CD203c and CD63 on milk-activated basophil were indeed much more pronounced in patients with severe allergy." (PMID 25002754, 2014). "After several improvements, the basophil activation test (using either CD203c or CD63 as activation marker) has become a robust and reliable test for in vitro investigations of immediate allergy, complementary to other existing in vitro tests." (PMID 15989690, 2005). "In our hands, in allergy to muscle relaxants, the results were quite interesting, since we found the sensitivity of the CD63 test was similar to that for specific IgE detection and higher than the one for histamine release test." (PMID 15989690, 2005). "Interestingly, we found that the combination of SPT and CD63-based BAT was better than, and improved diagnostic power compared to, using BAT or SPT alone in cases of black tiger shrimp allergy, which finding is clinically relevant." (PMID 40572728, 2025). "The study shows that BAT with Pru p 3 (assessing basophil activation by measuring CD63+) is an effective tool for confirming allergy to Pru p 3 and may have correlation with severity of clinical symptoms." (PMID 41226443, 2025). "Anti-CD63 antibodies were reported to suppress allergy or inhibit metastasis in vivo." (PMID 36542714, 2022). "There was evidence of sensitization to American ginseng on skin prick testing (SPT) (13 × 12 mm wheal) and evidence of allergy to American ginseng on basophil activation testing, with a dose-dependent increase in expression of CD63 on basophils in response to American ginseng extract." (PMID 30410551, 2018). "For BM allergy, the optimal cut‐off for BAT was 11.1% CD63+ basophils or SI CD203c of 1.88, with sensitivity/specificity of 91%/78% and 80%/90%, respectively." (PMID 40808324, 2025).
Allergy (continued). "Basophil activation, measured by CD63 upregulation and CD-Sens, demonstrated the clinical relevance of low sIgE levels to Pru p 3.BAT results correlated with the severity of allergic reactions." (PMID 41226443, 2025). "The surface expression of CD63, CD203c and CD69 is commonly used to assess human basophil activation upon acute hypersensitivity allergic reaction." (PMID 36685514, 2022). "iPer a 5 and bPer a 5 at 1.0 μg/mL induced approximately up to 4.5- and 3.2-fold increase in the expression of CD63 and CCR3 in CD63 and CCR3 double positive cells when incubating with passively sensitized basophils (by sera from American CR allergy)." (PMID 24707117, 2014). "Induction of upregulated expression of CD63 and CCR3 on passively sensitized human basophils (sera from American CR allergy patients) by approximately up to 4.5- and 3.2-fold indicates that iPer a 5 and bPer a 5 are functionally active." (PMID 24707117, 2014). "The first is an allergy study, in which EMD was used to determine clinically-relevant shifts in the expression of basophil surface markers (CD203c and CD63), whose expression is known to increase following hypersensitivity reaction to the Aspergillus fumigatus (A. fumigatus) allergen." (PMID 27008164, 2016). "CD63, compared to CD203c, is not a basophil-specific marker and has been shown to be less specific and less sensitive (in grass pollen and house dust mite allergy, latex allergy, wasp venom hypersensitivity, peanut allergy)." (PMID 27999658, 2016). "Compared with SPT and sIgE, CD63 expression-based BAT was better in discriminating subjects with allergies to these species from their non-allergic counterparts (AUC/sensitivity/specificity = 0.88/77%/89% for shrimp, and 0.74/88%/77% for prawn, p < 0.05 for all)." (PMID 40572728, 2025). "The significant correlations between sIgE levels and the percentage of basophils with the expression of CD63 were shown in only patients with milk (r = 0.493, p = 0.011) or egg (r = 0.339, p = 0.028) allergy, while the correlations were not in the others without milk and egg allergy." (PMID 33291359, 2020). "An allergy study, in which we show that EMD analysis of poorly coordinated shifts in the expression of two independent flow cytometry-measured basophil surface markers (CD203c and CD63) readily distinguishes patients allergic to a fungus from those who are not." (PMID 27008164, 2016). "In the absence of CD63, OCT3 will stay in the plasma membrane further releasing histamine and probably increasing severity of allergic reactions." (PMID 40652190, 2025).
ovarian carcinoma (26 papers, 2013 to 2025). A malignant neoplasm originating from the surface ovarian epithelium. "They demonstrated a 3–5-fold increase in EV-associated expressions of EpCAM, CA-125, CD9, CD81, and CD63 in ovarian cancer patients compared to healthy controls." (PMID 31212643, 2019). "While this association is novel to the best of our knowledge, CD63 is known to be an exosomal marker that correlates with invasiveness in ovarian cancer cell lines." (PMID 31136571, 2019). "Western blot analysis confirmed the presence of exosome-specific protein markers, including CD9, CD63, and tumor susceptibility gene 101 (TSG101), in ovarian cancer (OC) ascites." (PMID 41331197, 2025). "It was found that expression levels of EpCAM and CD24 of CD63+ sEVs were significantly higher in ovarian cancer patients compared with healthy controls." (PMID 37504087, 2023). "This includes differential inclusion of thecanonical exosome marker CD63, which was elevated in ovarian cancer exosomes butminimally included in lung cancer specimens." (PMID 36202098, 2023). "For this, we examined CD63 expression in ovarian cancer cells by immunofluorescence and found that downregulation of OGT significantly reduced the fluorescence intensity of CD63." (PMID 34001861, 2021). "This platform was able to efficiently capture EVs by anti-CD81 antibody and discriminate plasma EVs derived from ovarian cancer patients (n = 7) from the healthy controls (n = 5) by the mixture containing three biomarkers (CD63, CD81, and EpCAM)." (PMID 31212643, 2019). "The interaction of CD63-GFP containing exosomes with the ovarian cancer cell line SKOV3 was evaluated by flow cytometry." (PMID 31461486, 2019). "By using a 3D novel engineered ExoProfile chip, diagnostic power of seven markers (EGFR, HER2, CA125, FRα, CD24, EpCAM, and CD9 plus CD63) were evaluated with AUC = 1 in ovarian cancer derived exosomes." (PMID 31718609, 2019). "CD63-positive particles < 200 nm in diameter were observed in scanning electron micrographs of ovarian cancer ascites samples applied to the ExoComplete EV capture filterplate and correlate to size estimates from nanoparticle tracking analysis." (PMID 29499737, 2018). "In this study, we defined the release of exosomes from ovarian cancer cells as the accumulation (in exosome-free incubation medium) of CD63 and CD9 positive, particulate protein with a density of 1.15 to 1.19 g/ml." (PMID 24393345, 2014). "Similarly, the existence of the exosome markers, such as TSG101 and CD63, in the exosome of ovarian cancer patients and normal cases, was validated." (PMID 34690112, 2021). "By using ExoSearch, it was shown that ovarian cancer patients overexpressed the CA-125, EpCAM, CD9, CD81 and CD63 markers." (PMID 37504087, 2023). "The results showed significant levels of CD63 and CD9 expression on the surfaces of exosomes in ovarian cancer ascites." (PMID 36741380, 2022). "Western blotting showed that the expression of human CD63 protein was significantly higher in the OGT sh group, indicating that downregulation of OGT promoted the release of exosomes from the ovarian cancer cells in vivo." (PMID 34001861, 2021). "The clinical potential of nPLEX emerged from its high-level integration and multiplexing capacity as the label-free detection of ovarian cancer-derived EpCAM (+) and CD24 (+) relative to CD63(+) exosomes in ascites fluids." (PMID 31212754, 2019). "Integrated analysis of the overall exosome levels allowed the quantification of CD9 (+) and CD81(+) from human plasma in ovarian cancer (nano-IMEX) and NSCLC, and CD63(+) in pancreatic cancer (ExoChip)." (PMID 31212754, 2019). "This device was functionalized with CD63 or CD24 to capture EVs from ovarian cancer patient ascites (n=20) and noncancer patients (n=10)." (PMID 31212643, 2019).
ovarian carcinoma (continued). "While CD81 (as well as CD9 and CD63) is not universally present in all EVs, our previous work has shown that preselecting a subpopulation of plasma EVs using CD81 can reproducibly detect ovarian cancer-associated biomarkers using these nano-engineered microfluidic chips." (PMID 37884576, 2023). "To determine whether ROS influence the TME through tumor exosomal miRNAs, we treated ovarian cancer A2780 cells with or without H2O2, and purified A2780-derived exosomes characterized by positive exosomal markers CD63 and CD81, and a negative exosomal marker calnexin." (PMID 35086548, 2022).